GP5 (glycoprotein V platelet)
Diseases named in the same sentence as GP5 in open-access papers (continued):
Sharing a sentence is not in itself a finding about the gene and the disease.
tumor (17 papers, 2013 to 2026). "Previous research has shown that the patterns of GP5 and tumor necrosis are associated with poor histopathological characteristics and high residual disease rates." (PMID 37588658, 2023). "According to this classification, the quantity of GP4 or GP5 present in the tumor is a key determinant to assess the risk associated with this tumor." (PMID 31366128, 2019). "Genomic CDH1 alterations with loss of E‐cadherin expression are observed in several tumour types such as lobular mammary, plasmacytoid urothelial, and diffuse gastric carcinoma, and result in pathological morphologies similar to single‐cell GP5 PCa." (PMID 39428716, 2025). "However, when we subdivided these tumor foci by histological aggressivity (i.e., Gleason pattern, Gp), these positive associations generally decreased in effect size from Gp3 (N = 48) to Gp4 (N = 101) to Gp5 (N = 28)." (PMID 36181613, 2022). "In contrast, the intraprostatic distribution of GP12 PrCa differed greatly from GP5, with the tumor extending from posterior apex to posterior base and into both seminal vesicles, and only partially filled any given tissue block." (PMID 37828555, 2023). "GP5, a part of the receptor for von Willebrand factor, has been poorly studied in tumor and disease diagnosis." (PMID 36404333, 2022). "To validate the observed increase in LDHA expression in GP5 tumours, we analysed the nuclear expression of HIF-1α using IHC." (PMID 35075123, 2022). "Nested PCR using MY09/MY11 and GP5+/GP6+ as well as PGMY09/11 L1 consensus primers were performed to investigate the presence of HPV DNA in the tumours." (PMID 29580212, 2018). "Tumours were classified as HPV-positive if they contained HPV DNA (by GP5+/6+ PCR and/or ISH) and overexpressed p16." (PMID 23634887, 2013). "This may be explained by the reduced statistical power of tests that assessed the primary GP5 data due to the considerably lower number of primary GP5 tumours (n = 50) in the TCGA-PRAD dataset compared to primary GP3 (n = 197) and GP4 (n = 250) lesions." (PMID 35075123, 2022). "However, GP5 glands showed significantly higher overall MCT1 expression compared to GP4 glands due to both increased tumour epithelial and stromal expression, which is in agreement with previously published mRNA expression data showing increased MCT1 in high-grade disease." (PMID 35075123, 2022). "HC + SEQ detected HPV DNA in five samples (39%) the four that tested positive by PCR using the GP5+/GP6+ primers and one additional tumor (Tumor 13)." (PMID 38898085, 2024). "High-grade PIN lesions had the highest mean RS of 6.1 (SD 3.0) and the RS scores of invasive tumor glands were as follows: GP3: RS 4.6 (SD 3.4); GP4: RS 4.3 (SD 4.1) and GP5: RS 5.5 (SD 4.3)." (PMID 38310601, 2024). "In conclusion, GP5, CCT7, UQCRC1, PGD, GAPDH and LDHA have been found to play a role in tumor development, prognosis and even diagnosis in previous studies." (PMID 36404333, 2022). "While in one unpublished study of ours, using GP5+ and GP6+ primers that amplify a broad spectrum of HPV genotypes, we found 17 out of 136 FFPE oropharynx tumor samples were HPV positive." (PMID 35708339, 2022). "Nonetheless, the detection of abundant DNA of two relatively uncommon HPV types in a tumor that was positive by HC + SEQ but not by GP5+/GP6 + PCR illustrated the breadth of sensitivity of the contemporary HC + SEQ approach to detect HPV in tumors." (PMID 38898085, 2024).
adenocarcinoma (2 papers, 2005 to 2013). A common cancer characterized by the presence of malignant glandular cells. "Molecular detection of HPV DNA, using nested PCR amplification of a conserved region of the HPV L1 gene DNA with the consensus MY09/11 and GP5+/6+primers, revealed the presence of viral DNA in 91.47% (115 of 129 SCC and 3 of 4 adenocarcinoma)." (PMID 23953248, 2013). "This woman with a symptomatic adenocarcinoma, who was tested hrHPV negative by GP5+/6+ PCR EIA twice, revealed human papillomavirus (HPV) type 31 by E7 type-specific PCR in the baseline and follow-up smear." (PMID 15827553, 2005).
head and neck tumours (1 paper, 2018). "In the current study, we have used three different standard primer sets (MY09/MY11, GP5+/GP6+ and PGMY09/11) and nested PCR to detect HPV DNA in head and neck tumours, which increases the sensitivity compared to a single PCR reaction." (PMID 29580212, 2018).
GP5 also shares sentences with these, for which no sentence is quoted: Parkinson disease (3 papers); cardiovascular disease (2); dementia (2); ischemic stroke (2); systemic lupus erythematosus (2); Thrombocytopenia (2); Anxiety (1); bacterial infection (1); benign breast tumors (1); brain tumors (1); colorectal cancer (1); COVID-19 (1); diabetes (1); E. coli infection (1); epilepsy (1); esophageal squamous cell carcinoma (1); foot and mouth disease (1); glioma (1); Hypertension (1); hypovitaminosis D (1); intraductal carcinoma (1); lung carcinoma (1); lung disease (1); Macrothrombocytopenia (1); malaria (1); malignant brain tumors (1); malignant neoplasm of breast (1); myocardial infarction (1); oral squamous cell carcinomas (1); peripheral neuropathy (1).
A further 8 diseases each share a sentence with GP5 in 1 paper.